LGALS3BP (galectin 3 binding protein)
Diseases named in the same sentence as LGALS3BP in open-access papers (continued):
Sharing a sentence is not in itself a finding about the gene and the disease.
glioma (9 papers, 2014 to 2025). A benign or malignant brain and spinal cord tumor that arises from glial cells (astrocytes, oligodendrocytes, ependymal cells). "Three proteins, CA9, CYFIP2, and LGALS3BP, were found to be associated with glioma progression and, in univariate analysis, could be used as prognostic markers." (PMID 38473425, 2024). "LGALS3BP, especially, is upregulated in EVs from glioma patients and has the potential for early glioma detection (sensitivity 77.8%, specificity 35.5%)." (PMID 41373835, 2025). "In cancer, the majority of research has focussed on the secreted versions of LGLAS3BP, with LGALS3BP found in plasma, a proposed biomarker for early detection and overall survival in glioma patients." (PMID 38473425, 2024). "Together as a panel, CA9, CYFIP2, and LGALS3BP were able to be used as a multi-gene prognostic index, highlighting the utility of these three molecules for predicting prognoses of glioma patients." (PMID 38473425, 2024). "The present research provides a galectin-3 binding protein (LGALS3BP) as novel biomarker for early detection of glioma (brain tumor)." (PMID 34900729, 2021). "LGALS3BP was seen to be upregulated across the different grades, and ELISA analysis from individual blood plasma and plasma-derived extracellular vesicles confirmed the increased expression of LGALS3BP in glioma patients (p<0.001)." (PMID 34900729, 2021). "An interesting finding of the proteomic analysis was that galectin binding protein (LGALS3BP) was seen to be upregulated across different grades of glioma." (PMID 34900729, 2021). "We found galectin-3 binding protein (LGALS3BP) as novel circulating biomarker for the detection of glioma at early grade and provide the information of progression in tumor grades." (PMID 34900729, 2021). "The present study provides LGALS3BP as a potential biomarker for early detection of glioma and improve survival outcome of the patient." (PMID 34900729, 2021). "Moreover, vesicular LGALS3BP expression levels measured in patient plasma correlate with glioma grade and progression." (PMID 37195369, 2023). "In the present study, various techniques were performed to characterize the extracellular vesicles; also, the expression of galectin-3 binding protein derived from plasma EVs was found to be strikingly high in patients having various grades of glioma as compared to healthy individuals." (PMID 34900729, 2021). "In addition to these well-established glioma markers, we identified several other proteins that have never been associated with glioma biology including (e.g., SLC1A3, CLU, LGALS3BP, ANGPTL2, CRYAB and ITGB8)." (PMID 25360666, 2014). "Furthermore, the functional LGALS3BP pathway may act as target to either augment for repair and scar reduction to avoid conditions such as epilepsy development, and/or to reduce its longer-term presence to avoid glioma formation." (PMID 38066208, 2023). "We further verified galectin-3 binding protein (LGALS3BP) by ELISA in individual blood plasma and plasma-derived vesicles from control and glioma patients (n=40 each)." (PMID 34900729, 2021). "Although there are a number of studies reported that suggest the involvement of Galectin-3 in gliomas, the LGALS3BP is not widely studied yet." (PMID 34900729, 2021).
neuroblastoma (9 papers, 2020 to 2025). Neuroblastoma (NB) is the most common solid, extracranial childhood tumor. "Notably, significantly elevated expression of LGALS3BP in the serum or tumor tissue has been found to be associated with poor clinical outcome in patients with a variety of malignancies, including neuroblastoma." (PMID 33076448, 2020). "A second metastatic model usingSKNAS neuroblastoma cells, which endogenously express LGALS3BP, wasutilized to study the kinetics of the payload." (PMID 41179189, 2025). "The potential therapeutic benefit of MDP1959-mediated inhibition of LGALS3BP for the treatment of human neuroblastoma was highlighted in different experimental models." (PMID 38066208, 2023). "Researchers from De Clarke’s lab published two studies on LGALS3BP role in neuroblastoma a few years apart from each other." (PMID 34565385, 2021). "Intriguing, it has been proposed a functional role for LGALS3BP expressed at the surface of neuroblastoma-derived exosomes, that is the ability to induce the production of IL-6 in a RAS/MEK/ERK-dependent manner." (PMID 34565385, 2021). "In conclusion, these results validated LGALS3BP as marker of treatment response and as potential target for neuroblastoma immunotherapy, given its immunogenicity." (PMID 34565385, 2021). "To further validate the plasma vesicles preparations, we used an antibody against galectin-3-binding protein (Gal-3BP), which was shown to detect exosomes secreted by neuroblastoma cells." (PMID 34847775, 2021). "They showed that LGALS3BP was expressed and secreted by neuroblastoma cell lines and, more importantly, by metastatic neuroblasts isolated from bone marrow samples." (PMID 34565385, 2021). "Studies have shown that LGALS3BP is enriched in extracellular vesicles (EV)s derived by most neuroblastoma cells, where it plays a critical role in preparing a favorable tumor microenvironment (TME) through direct cross talk between cancer and stroma cells." (PMID 33076448, 2020). "In this study, we confirmed that LGALS3BP is expressed by the vast majority of classical and patient-derived neuroblastoma cell lines." (PMID 33076448, 2020). "The data presented here, strongly encourage further development of this ADC targeting exosomal LGALS3BP in neuroblastoma." (PMID 33076448, 2020). "Accordingly, it has been recently observed that serum levels of LGALS3BP are increased compared to controls in patients with neuroblastoma." (PMID 33076448, 2020). "1959-sss/DM3 ADC showed potent and specific therapeutic activity in multiple models of LGALS3BP expressing human neuroblastoma." (PMID 33076448, 2020). "Recent studies have revealed that LGALS3BP plays a key role in the cross-talk between neuroblastoma cells and the tumor microenvironment (TME)." (PMID 33076448, 2020). "In agreement with previous reports, LGALS3BP was expressed in neuroblastoma cell lines, independently of MYCN amplification." (PMID 33076448, 2020). "In the first study, they identified and isolated LGALS3BP from serum-free conditioned medium of several neuroblastoma cells, and proved that it stimulated expression of IL-6 followed by an increase in Erk1/2 activation in human bone marrow stromal cells (BMSC) expressing its receptor Galectin-3." (PMID 34565385, 2021). "Additionally, neuroblastoma was the cancer context in which LGALS3BP was identified as extracellular ligand of endosialin (also known as Tumor Endothelial Marker 1, TEM-1)." (PMID 34565385, 2021). "We analyzed LGALS3BP expression at mRNA and protein level in a panel of neuroblastoma cell lines." (PMID 33076448, 2020). "If validated by further safety studies, 1959-sss/DM3 could be added to the arsenal of immunotherapeutics for treatment of neuroblastoma and, potentially, other malignancies expressing LGALS3BP." (PMID 33076448, 2020).
neuroblastoma (continued). "Here, we describe the therapeutic activity of 1959-sss/DM3, a non-internalizing ADC targeting LGALS3BP, a secreted, extracellular vesicles-associated protein expressed by the majority of human cancers, including neuroblastoma." (PMID 33076448, 2020). "Indeed, we have recently reported that high expressing LGALS3BP melanoma and neuroblastoma can be effectively treated with DM3 and DM4 maytansinoid‐based ADCs directed against LGALS3BP." (PMID 37195369, 2023). "To better evaluate the potential of the novelHPLC method developed, we employed a second pseudometastatic modelof neuroblastoma using the SKNAS cell line, which endogenously expressesa considerable amount of LGALS3BP." (PMID 41179189, 2025). "Was employeda patient-derived neuroblastoma cell line (hNB CTRL), which naturallylacks LGALS3BP expression, alongside a counterpart cell line (hNBLGALS3BP) in which LGALS3BP expression was ectopically induced vialentiviral-mediated gene transduction." (PMID 41179189, 2025). "More recently, in light of new findings on the abundance of LGALS3BP in extracellular vesicles in several cancers, we investigated the therapeutic potential of 1959-sss/DM3 in multiple pre-clinical models of human neuroblastoma expressing vesicular LGALS3BP." (PMID 34565385, 2021). "The results presented in this investigation demonstrate that a newly developed ADC targeting LGALS3BP has the potential to eradicate metastatic and MYCN amplified neuroblastomas in preclinical mouse models." (PMID 33076448, 2020). "In conclusion, the results presented in this study validate LGALS3BP as a suitable target for ADC therapy and provides a rationale for further clinical development of an anti-LGALS3BP based ADC for the treatment of neuroblastomas." (PMID 33076448, 2020). "Additionally, our recent works documented that LGALS3BP targeting antibody–drug conjugate (ADC) showed potent therapeutic activity against melanoma and neuroblastoma xenografts." (PMID 37195369, 2023). "We and others have previously ascertained that LGALS3BP is expressed in tumor cells and the extracellular matrix in the majority of neuroblastoma biopsies, but it is not accumulated in adjacent normal tissues." (PMID 33076448, 2020). "Here, we describe the development of a non-internalizing LGALS3BP ADC, named 1959-sss/DM3, which selectively targets LGALS3BP expressing neuroblastoma." (PMID 33076448, 2020). "Using confocal imaging, we confirmed that LGALS3BP co-localizes with the exosome markers CD-63 and CD-81 and its mature form is enriched in exosomes/EVs isolated from SKNAS but not hNB neuroblastoma cells, providing an opportunity for specific targeting with 1959 antibody." (PMID 33076448, 2020).
Cirrhosis (8 papers, 2016 to 2022). A chronic disorder of the liver in which liver tissue becomes scarred and is partially replaced by regenerative nodules and fibrotic tissue resulting in loss of liver function. "LGALS3BP, which was up‐regulated in NAFLD and T2D, is a candidate biomarker for hepatitis C‐related fibrosis and cirrhosis." (PMID 30824564, 2019). "Plasma proteome profiling of 48 patients with and without cirrhosis or NAFLD revealed six statistically significantly changing proteins (ALDOB, APOM, LGALS3BP, PIGR, VTN, and AFM), two of which are already linked to liver disease." (PMID 30824564, 2019).
liver disease (8 papers, 2017 to 2026). "The elevated levels of LGALS3BP and vitronectin (VTN), another extracellular matrix (ECM) protein, are likely a reflection of remodeling of the ECM in liver disease." (PMID 30824564, 2019).
lung carcinoma (8 papers, 2015 to 2024). "They analyzed LGALS3BP serum levels from 320 lung cancer patients and 80 healthy donors, confirming the potential value of this protein as a serological marker for lung cancer." (PMID 34565385, 2021). "Together with breast and lung cancer, melanoma was one of the first malignancies where LGALS3BP was originally detected." (PMID 34565385, 2021). "Another study reported that 87.5% of lung carcinoma cell lines and 60.7% of tumor tissues expressed high levels of LGALS3BP mRNA and that there was a correlation of LGALS3BP protein with clinical stage (stage I and II: 27.8%; stage III and IV: 60%)." (PMID 34565385, 2021). "Calu-1 human lung cancer cells were among the first cell lines where LGALS3BP was identified as an antigen recognized by L3 antibody." (PMID 34565385, 2021). "A research group showed that the mean LGALS3BP level was significantly higher in MM pleural effusions than the levels detected in lung cancer or benign pleural disease patients." (PMID 34565385, 2021). "Breast and lung cancer cells overexpressing LGALS3BP demonstrated resistance to apoptosis in response to cisplatin." (PMID 29868478, 2018). "It is reported LGALS3BP can induce 17-N-Allylamino-17-demethoxygeldanamycin resistance in lung cancer cell Line, but the detailed mechanism is unknown." (PMID 35038949, 2022). "The difference in LGALS3BP expression between MM and lung cancer was confirmed by immunostaining, but without a significative difference between early and advanced stage disease." (PMID 34565385, 2021). "Finally, LGALS3BP appeared to be involved in resistance to 17-AAG (17-N-Allylamino-17- demethoxygeldanamycin), an HSP90 inhibitor tested in phase II/III clinical trials in lung cancer." (PMID 34565385, 2021).
glioblastoma (7 papers, 2019 to 2025). The most malignant astrocytic tumor (WHO grade IV). "Among the differential expressed 801 glycoproteins, they found LGALS3BP for the first time reported associated to glioblastoma." (PMID 34565385, 2021). "LGALS3BP is regarded as a glioblastoma stem cell-associated marker, and a CD9 ligand." (PMID 35454889, 2022). "A study aiming to characterize the secretome of glioblastoma-derived neural stem cells (GNS) identified LGALS3BP protein to be upregulated in GNS cells." (PMID 35454889, 2022). "In the current study, we tried to study the expression of LGALS3 and LGALS3BP, their potential as prognostic markers and the possible genetic/epigenetic mechanisms underlying their dysregulation in different subtypes of glioblastoma (GBM)." (PMID 30848102, 2019). "In the current study, we tried to study the expression of LGALS3 and LGALS3BP, their potential as prognostic markers and the possible genetic/epigenetic mechanism underlying their dysregulation in different subtypes of glioblastoma (GBM), by using large online databases." (PMID 30848102, 2019). "LGALS3BP expression is also elevated in carcinogenesis, including lung, breast, glioblastoma multiforme (GBM) and others." (PMID 39062523, 2024). "LGALS3BP is overexpressed in glioblastoma multiforme (GBM) and is highly enriched in GBM‐derived extracellular vesicles." (PMID 37195369, 2023). "We identified the following five proteins that were present in all samples, both glioblastoma-derived EVs and HPA-derived EVs: THBS1, FN1, TGFBI, ACTN4, and LGALS3BP." (PMID 35454889, 2022).
Obesity (6 papers, 2016 to 2021). Accumulation of substantial excess body fat. "Galectin-3-binding protein (GAL-3BP) is a ubiquitous and multifunctional secreted glycoprotein, which functions in innate immunity and has been highlighted as a potential mediator of adipose inflammation in obesity." (PMID 34858323, 2021).
atherosclerosis (5 papers, 2017 to 2025). A disease characterized by the build-up of fatty material and calcium deposition in the arterial wall resulting in partial or complete occlusion of the arterial lumen. "Finally, we confirmed that hepatocyte‐specific knockout of Lgals3bp significantly inhibited MAFLD‐associated atherosclerosis and calcification." (PMID 39680681, 2025). "ORO staining of the whole aorta, aortic arch microscopy, and aortic sinus staining showed that the inhibition of Lgals3bp expression in hepatocytes significantly attenuated atherosclerosis." (PMID 39680681, 2025). "Steatotic hepatocytes‐derived extracellular vesicles (SHep‐EVs) in the liver of mice with metabolic dysfunction‐associated fatty liver disease (MAFLD) can be transferred to vascular smooth muscle cells (VSMCs), exacerbating atherosclerosis and calcification by delivering Lgals3bp." (PMID 39680681, 2025). "Up-regulated DEGs included known atherosclerosis genes such as the liver X receptor gene NR1H2, and NEXN, TRAF1, TLR7 and LGALS3BP, implicating tumor necrosis factor and toll-like receptor signaling and glycan-binding protein pathways." (PMID 37205656, 2023).
Ewing sarcoma (5 papers, 2015 to 2024). A small round cell tumor that lacks morphologic, immunohistochemical, and electron microscopic evidence of neuroectodermal differentiation. "For example, engineered enhancement of LGALS3BP expression resulted in significant tumor growth inhibition and high levels of LGALS3BP expression in tumor tissue were associated with a favorable outcome in a series of patients with Ewing’s sarcoma." (PMID 26219351, 2015). "For example, though high serum LGALS3BP levels are associated with poor clinical outcomes in patients with breast, hepatocellular, and non-small cell lung carcinoma, high LGALS3BP expression in tumor tissues is associated with favorable outcomes in patients with Ewing’s sarcoma and CRC21,22." (PMID 33824294, 2021). "Another type of cancer in which LGALS3BP seemed to have a favorable prognostic value is Ewing’s sarcoma (EWS)." (PMID 34565385, 2021). "It should be also noted that previous reports showed that Ewing’s sarcoma secrete exosomes including galectin-3-binding protein (LGALS3BP), and it may be a candidate of favorable prognostic indicator, as neutralizing the molecular function of Gal-3." (PMID 32929561, 2021).
lymphoma (5 papers, 2013 to 2023). A malignant (clonal) proliferation of B- lymphocytes or T- lymphocytes which involves the lymph nodes, bone marrow and/or extranodal sites. "Indeed they showed that high production and deposition of LGALS3BP by lymphoma cells in extracellular matrix protected tumor cells against cytotoxic drugs." (PMID 34565385, 2021). "In the future, it would be important to study whether high sera levels of LGALS3BP could be associated with other viral associated malignancies such as EBV-associated nasopharyngeal carcinomas and lymphomas." (PMID 32542012, 2020). "Moreover, they proved a role for LGALS3BP in mediating lymphoma cell resistance to chemotherapy." (PMID 34565385, 2021).
oral cancer (5 papers, 2017 to 2025). "Data also indicates that NUS1, RCN1, endothelin-1, ANG, transgelin, FSA, PBSA, KPNA2, LGALS3BP, vitamin C, L-fucose, CYFRA 21-1, β2-microglobulin, and cathepsin B mRNAs also demonstrate variable expression in the saliva of patients with oral cancer." (PMID 40723410, 2025).
hepatitis C virus infection (4 papers, 2017 to 2022). A viral infection caused by the hepatitis C virus. "Notably, LGALS3BP is associated with carotid artery disease in patients with human immunodeficiency virus and hepatitis C virus infection." (PMID 28319050, 2017). "LGALS3BP has already been used to build multi‐component classifiers for the prediction of NAFLD and fibrosis in patients with hepatitis C infection." (PMID 30824564, 2019).
melanoma (4 papers, 2015 to 2023). A malignant, usually aggressive tumor composed of atypical, neoplastic melanocytes. "A large body of evidence shows that high LGALS3BP expression in tissues and serum are associated with unfavourable clinical outcomes in a wide variety of malignancies, including breast, lung, ovarian, pancreatic, prostatic, liver, gastric cancers and melanoma." (PMID 37032358, 2023). "Initially, the protein was identified as a cytoplasmic melanoma-associated antigen (CYT-MAA) and considered to be different from LGALS3BP." (PMID 34565385, 2021). "In conclusion, measurement of LGALS3BP serum level appeared to show potential as an early marker of prognosis in patients with stages IIb to IV melanoma and, mostly, an intermediate marker of response in these patients." (PMID 34565385, 2021). "Regarding clinical significance, a first study examined LGALS3BP serum level in 128 melanoma patients during immunotherapy." (PMID 34565385, 2021). "From the biological viewpoint, A375 melanoma cells served as a model to demonstrate LGALS3BP mediated cell–cell adhesion and homotypic cell aggregation via bridging galectin-3 on the cell surface in a specific carbohydrate-dependent manner." (PMID 34565385, 2021). "Three 1959-sss/based ADC products were obtained using as payloads the maytansinoid thiol-derivatives DM1-SH, DM3-SH and DM4-SH and tested on LGALS3BP+ melanoma xenograft model." (PMID 34565385, 2021). "By contrast, there was no decline in LGALS3BP serum level in 11 melanoma patients who served as untreated controls." (PMID 34565385, 2021).